PAK5 (p21 (RAC1) activated kinase 5)
Diseases named in the same sentence as PAK5 in open-access papers (continued):
Sharing a sentence is not in itself a finding about the gene and the disease.
glioma (9 papers, 2015 to 2025). A benign or malignant brain and spinal cord tumor that arises from glial cells (astrocytes, oligodendrocytes, ependymal cells). "For instance, knockdown of PAK5 in human glioma cells inhibited cell migration and invasion by interacting with EGR1-MMP2 signaling." (PMID 30245957, 2018). "Reports in recent years have shown that PAK5 can promote proliferation by G1 arrest prevention in types of cancers such as hepatocellular carcinoma, gastric cancer, glioma, and osteosarcoma." (PMID 29041983, 2017). "XIAP (X-linked inhibitor of apoptosis, a class of anti-apoptotic proteins), and PAK7 (also known as PAK5, an evolutionarily conserved serine/threonine protein kinase), were highly expressed in glioma cells." (PMID 32195180, 2020). "PAK7 (also known as PAK5), an evolutionarily conserved serine/threonine protein kinase, is highly expressed in glioma cells and promotes the cell proliferation, migration, invasion as well as inhibiting apoptosis." (PMID 26231038, 2015).
renal cell carcinoma (8 papers, 2017 to 2024). "For example, miR-106a-5p has been reported to inhibit the migration and invasion of renal cell carcinoma through targeting PAK5." (PMID 34603447, 2021). "Besides, miR-106a-5p/PAK5 pathway reduced the migrated ability and invasive ability of renal cell carcinoma." (PMID 38358587, 2024).
hepatocellular carcinoma (7 papers, 2017 to 2026). A malignant tumor that arises from hepatocytes. "PAK5 resists apoptotic signals to promote chemoresistance induced by cisplatin in hepatocellular carcinoma via regulating CHK2." (PMID 36830998, 2023). "Thus, we demonstrated that miRNA-138-1-3p sensitizes sorafenib to hepatocellular carcinoma by targeting PAK5 mediated β-catenin/ABCB1 signaling pathway." (PMID 34340705, 2021). "Nevertheless, the deep deletions observed for PAK5 and PAK6 in cancers such as pancreatic and prostate raise the possibility that these isoforms may function as tumor suppressors in certain contexts as has been suggested in hepatocellular carcinoma, a hypothesis that warrants further investigation." (PMID 39756822, 2025).
gastric cancer (6 papers, 2014 to 2017). A primary or metastatic malignant neoplasm involving the stomach. "It has also been reported that PAK5 might contribute to gain of tumor growth potential, acting by affecting the expression of Cyclin D1 in gastric cancer." (PMID 29041983, 2017). "PAK5 is reported to be overexpressed in colorectal and gastric cancer." (PMID 27542207, 2016).
lung carcinoma (6 papers, 2014 to 2025). "Targeted genetic dependency screen is an efficient approach to identify somatic cancer alterations and was used to identify gain-of-function (GOF) mutations in lung cancer for FGFR4, MAP3K9, and PAK5 kinases." (PMID 24817905, 2014). "P21-activated kinase 7 (PAK7), also known as PAK5, is an essential member of the PAK Ser/Thr kinase family, which is found to be overexpressed in various types of cancers, including lung cancer, and is considered as an oncogene." (PMID 35242138, 2022).
prostate carcinoma (5 papers, 2013 to 2025). A carcinoma that arises from epithelial cells of the prostate gland. "Our finding that PAK5 deletions were associated with poorer survival in prostate cancer further highlights the need for more focused investigations into the functional consequences of these alterations." (PMID 39756822, 2025). "The deep deletions observed in PAK5 and PAK6, particularly in pancreatic and prostate cancers, point to the possibility that these isoforms may act as tumor suppressors." (PMID 39756822, 2025).
melanoma (4 papers, 2014 to 2022). A malignant, usually aggressive tumor composed of atypical, neoplastic melanocytes. "In multiple cancers including melanomas PAK5 most frequently carries non-synonymous mutations; PAK6 and PAK4 have fewer; and PAK4 is often amplified." (PMID 35969127, 2022). "Our findings show that although the kinase activity of common, melanoma-associated PAK5 mutants is unaltered in vitro, a subset of these variants (PAK5 S364L and D421N) are able to promote melanocyte proliferation." (PMID 29875996, 2018). "Beyond single nucleotide variants, 5.1% of melanomas exhibit elevated PAK5 mRNA levels similar to the increased expression of other PAK family members in human cancer." (PMID 29875996, 2018). "This domain extends from amino acids 351 to 445, is serine-rich (28%), and harbors 23% of all PAK5 missense mutations reported in the provisional TCGA melanoma dataset." (PMID 29875996, 2018). "Kinase activity of the melanoma-associated PAK5 mutants, E144K, M173I, E294K, S364L, and D421N, was similar to the wildtype control." (PMID 29875996, 2018). "In accordance with this model, it remains possible that melanoma-associated PAK5 mutants alter single-cell migration and/or temozolomide resistance in the context of specific cancer proteomes." (PMID 29875996, 2018). "To determine if common melanoma-associated PAK5 mutations affect enzymatic function, we immunoprecipitated individual PAK5 mutants from our hMELT stable cell lines and subjected these proteins to in vitro kinase assays using a canonical PAK4 peptide substrate." (PMID 29875996, 2018). "More than 60% of melanoma-associated PAK5 gene alterations are missense mutations, and distribution of these variants throughout the protein coding sequence make it difficult to distinguish oncogenic drivers from passengers." (PMID 29875996, 2018). "Based upon mutational rates published by TCGA, the 2,160 base pair PAK5 coding sequence should be randomly mutated in 3.6% of melanoma cases." (PMID 29875996, 2018). "Most melanoma-associated PAK5 alterations were missense mutations (62%), localized throughout the protein coding sequence within both the PBD and kinase domain as well as uncharacterized regions." (PMID 29875996, 2018). "To address this issue, we stably introduced the five most common melanoma-associated PAK5 missense mutations into human immortalized primary melanocytes (hMELTs)." (PMID 29875996, 2018). "In the genomes of specific cancers, namely breast, head-and-neck, liver, lung adenocarcinoma, squamous cell lung cancer, and melanomas, PAK5 frequently carries non-synonymous point mutations, and small insertions and deletions; PAK6 and PAK4 have fewer; and PAK4 is often amplified." (PMID 35969127, 2022). "However, we find that 15% of melanomas contain a PAK5 missense mutation, suggesting that alterations in this gene are advantageous to tumor development and/or progression." (PMID 29875996, 2018). "Taken together, these data show that PAK5 is the most frequently mutated PAK in human melanoma." (PMID 29875996, 2018). "PAK5 missense mutations are evenly distributed throughout characterized and uncharacterized domains of the protein, making it difficult to predict the functional consequences of these alterations in melanoma." (PMID 29875996, 2018). "Together these genomic, biochemical and cellular data suggest that the oncogenic properties of PAK4 are regulated by PKC–PKD signalling in melanoma, while PAK5 and PAK6 are dispensable in this cancer." (PMID 35969127, 2022). "PAK4 and PAK6 are expressed to different levels in different melanoma cell lines, while PAK5 expression is low or undetectable in these cells." (PMID 35969127, 2022). "While PAK5 alterations are rare in tumor types other than melanoma, the mutants characterized by our study appear in additional tumor sequencing datasets." (PMID 29875996, 2018). "Here, we identify p21-activated serine/threonine kinase 5 (PAK5) as the most frequently altered PAK family member in human melanoma." (PMID 29875996, 2018).
melanoma (continued). "This enrichment was unique to melanoma, as PAK5 alterations were infrequent in other TCGA-analyzed tumor types (<9%)." (PMID 29875996, 2018). "To elucidate these functions, we characterized the most frequently observed PAK5 mutants in human melanoma (E144K, M173I, E294K, S364L, and D421N)." (PMID 29875996, 2018). "In contrast with PAK4, PAK5 was undetectable in the melanoma cells and its ectopic expression did not rescue the loss of PAK4." (PMID 35969127, 2022). "However, because the p16-CDK4/6-Rb axis is deregulated in ∼70% of melanomas, our hMELT stable lines provided an excellent backdrop for the discovery of clinically relevant pathways engaged by mitogenic PAK5 mutants." (PMID 29875996, 2018). "To investigate this hypothesis, here we compare the cellular regulation of PAK4, PAK5 and PAK6, and investigate their relative roles in melanoma cells." (PMID 35969127, 2022). "To determine whether melanoma-common PAK5 mutants confer resistance to temozolomide, an alkylating chemotherapeutic drug approved for the treatment of malignant melanoma, we first ascertained the IC50 of temozolomide in hMELT cells expressing wildtype PAK5 (250 μM)." (PMID 29875996, 2018). "Together these findings indicate that only PAK4, but not PAK5 and PAK6, can complement the requirement for survival and migration of melanoma cells." (PMID 35969127, 2022).
colon carcinoma (3 papers, 2016 to 2020). "Gain and loss of function experiments of PAK5 in the SW480 colon cancer cell line revealed that PAK5 reduced cell adhesion but promoted their migration." (PMID 32178475, 2020). "Of great interest, evidence also showed that PAK5 promotes epithelial-to-mesenchymal transition in several types of cancer such as colon cancer and bladder cancer." (PMID 30245957, 2018).
ovarian carcinoma (3 papers, 2014 to 2025). A malignant neoplasm originating from the surface ovarian epithelium. "PAK5 was initially found to be overexpressed in clinical ovarian cancer, and PAK5 expression is associated with distant metastasis and poor prognosis." (PMID 30245957, 2018). "Our data suggested that PAK5 regulated the activation process of the PI3K/AKT pathway; in other words, PI3K/AKT signaling might underlie the molecular mechanism that contributed to PAK5-mediated ovarian cancer progression." (PMID 30245957, 2018). "Elevated expression of PAK5 has been observed in ovarian cancer tissues, particularly in cases with distant metastasis, correlating with poorer patient survival." (PMID 40740483, 2025). "Our observations suggested that PAK5 induced epithelial-to-mesenchymal transition and promoted cell migration and invasion in ovarian cancer." (PMID 30245957, 2018). "The present study was aimed at investigating the expression profile of PAK5 in clinical ovarian cancer and at examining its functional roles in ovarian cancer cell epithelial-to-mesenchymal transition and migration and invasion." (PMID 30245957, 2018). "All these observations suggested that PAK5 promoted the epithelial-to-mesenchymal transition in ovarian cancer cell lines." (PMID 30245957, 2018). "The present study investigated the expression level of PAK5 in clinical ovarian cancer and the functional roles of PAK5 in ovarian cancer progression." (PMID 30245957, 2018). "qRT-PCR analysis also showed that the mRNA level of PAK5 was differentially expressed in a series of ovarian cancer cell lines, including SKOV3, A2780, OVCR, HRA, and COC1, whereas the highest level presented in SKOV3 cells and the least level in A2780 cells." (PMID 30245957, 2018). "Higher expression of PAK5 predicted poor survival fates in patients with ovarian cancer (p = 0.008)." (PMID 30245957, 2018). "IHC analysis showed that PAK5 was significantly stained in ovarian cancer tissues, while it was barely detected in normal tissue." (PMID 30245957, 2018). "It was initially found that PAK5 was highly expressed in ovarian cancer tissues, particularly in patients with distant metastasis." (PMID 30245957, 2018). "These clinical observations suggested that PAK5 was highly expressed in ovarian cancer and predicted poor prognosis." (PMID 30245957, 2018). "In all, the present study identified PAK5 as a critical mediator of ovarian cancer cell migration and invasion." (PMID 30245957, 2018). "The oncogenic potential of PAK5 in ovarian cancer might suggest that any therapeutic strategies targeting PAK5 had the promising value for ovarian cancer treatment." (PMID 30245957, 2018). "PAK5 also induced epithelial-to-mesenchymal transition in ovarian cancer cells." (PMID 30245957, 2018). "Our data suggested that any therapeutic strategies against PAK5 might serve as a promising avenue to the treatment of ovarian cancer." (PMID 30245957, 2018). "Recently, it has been reported that PAK5 overexpression promotes paclitaxel chemoresistance of epithelial ovarian cancer, suggesting that PAK5 may also have a role in the regulation of ovarian cancer." (PMID 30245957, 2018). "Small inhibitors targeting the PI3K/AKT activation might also blunt PAK5-mediated biological activities and open novel insights into ovarian cancer treatment." (PMID 30245957, 2018). "In the present study, we identified PAK5 as a critical mediator of ovarian cancer progression." (PMID 30245957, 2018). "One such regulatory molecule is PAK5 (P21 (RAC1) Activated Kinase 5) (PAK5)F‐box protein 11, whose role in EMT and metastasis has been extensively studied in ovarian cancer." (PMID 40740483, 2025). "Our loss-of-function and gain-of-function studies indicated that PAK5 induced epithelial-to-mesenchymal transition and promoted cell migration and invasion by activating the PI3K/AKT pathway in ovarian cancer." (PMID 30245957, 2018).
pancreatic cancer (3 papers, 2017 to 2025). "Interestingly, in pancreatic cancer, PAK4 exhibited the highest frequency of alterations (10%), a notable increase compared to PAK2 (4%) and PAK3 (1%), while PAK1, PAK5, and PAK6 were altered in fewer than 1% of cases." (PMID 39756822, 2025). "There is not enough supporting literature on PAK5 and PAK6 in pancreatic cancer, but the data suggests that these PAK isoforms may play important roles in cellular differentiation and apoptosis." (PMID 39756822, 2025).
lung adenocarcinoma (2 papers, 2018 to 2022). A carcinoma that arises from the lung and is characterized by the presence of malignant glandular epithelial cells. "Specifically, PAK5 E144K has been observed in colorectal adenocarcinomas, PAK5 S364L in lung adenocarcinomas, colon adenocarcinomas, and uterine endometrioid tumors, and PAK5 D421N in multiple lung adenocarcinomas." (PMID 29875996, 2018).
neuroblastoma (2 papers, 2011 to 2017). Neuroblastoma (NB) is the most common solid, extracranial childhood tumor. "Altered Pak5 nucleocytoplasmic shuttling, for example, changed the sensitivity of neuroblastoma cells and neural stem cells to apoptosis." (PMID 22128240, 2011). "However, we did not observe altered intracellular distribution of PAK5 in the degenerating retina (data not shown), suggesting that a CDC42-dependent PAK5 translocation mechanism similar to neuroblastoma may not be involved in photoreceptor apoptosis." (PMID 22128240, 2011).
Anxiety (1 paper, 2021). Intense feelings of nervousness, tension, or panic often arise in response to interpersonal stresses. "Further studies with PAK proteins in mice correlated PAK1, but not PAK5 and PAK6, with anxiety-related phenotypes." (PMID 34125184, 2021).
Cerebral ischemia (1 paper, 2025). Restriction of arterial blood supply to the brain associated with insufficient oxygenation to support the metabolic requirements of the tissue. "Finally, activation in axons of PAK5 synthesis and signaling after spinal cord injury or cerebral ischemia protects neurons from an axonal energy crisis by reprogramming mitochondrial trafficking and anchoring." (PMID 40225562, 2025).
clear cell renal cell carcinoma (1 paper, 2023). "PAK4, PAK5, and PAK6 are homologs of CLA4, and PAK6 has also been implicated in clear cell renal cell carcinoma." (PMID 36598488, 2023).
endometriosis (1 paper, 2025). The growth of functional endometrial tissue in anatomic sites outside the uterine body. "In addition, p21-activated kinase 5 (PAK5) increases the protein stability of PKM2; thus, inhibiting PAK5 with GNE 2661 inhibited glycolysis and growth in endometriosis." (PMID 40573210, 2025).
head and neck squamous cell carcinoma (1 paper, 2025). A squamous cell carcinoma that arises from any of the following anatomic sites: lip and oral cavity, nasal cavity, paranasal sinuses, pharynx, larynx, and salivary glands. "Further supporting this mechanism, sodium bicarbonate cotransporter 3 (SLC4A7)PAK5 (P21 (RAC1) Activated Kinase 5) has been implicated in EMT induction and metastatic behavior in head and neck squamous cell carcinoma (HNSCC)." (PMID 40740483, 2025).
ischemia (1 paper, 2022). A hypoperfusion of the BLOOD through an organ or tissue caused by a PATHOLOGIC CONSTRICTION or obstruction of its BLOOD VESSELS, or an absence of BLOOD CIRCULATION. "In contrast, newly synthesized Miro-1 in axons showed no significant change following the same OGD-R conditions, indicating that axonal PAK5 synthesis and local signaling is transiently activated in response to ischemia." (PMID 36184647, 2022). "We recently revealed that activated PAK5 signaling mediates a local phosphorylation switch that turns off SNPH-anchoring and remobilizes ischemia-damaged axonal mitochondria for replacement with healthy ones, thus reversing the injury-induced energy crisis." (PMID 36184647, 2022).
leiomyosarcoma (1 paper, 2023). An uncommon, aggressive malignant smooth muscle neoplasm, usually occurring in post-menopausal women. "In the leiomyosarcoma sample, the genes involved in cell growth, survival, and proliferation (MFHAS1, YAF2, SOX5, and PAK5) were also overexpressed." (PMID 36673024, 2023).
memory impairment (1 paper, 2013). "This suggests that both the Pak5 gene and the Pak6 gene need to be knocked out for learning and memory impairments." (PMID 23593460, 2013).
cancer (26 papers, 2008 to 2025). A tumor composed of atypical neoplastic, often pleomorphic cells that invade other tissues. "Only one other report has examined the role of PAK5 missense mutations in cancer prior to our study." (PMID 29875996, 2018). "PAK5 (formerly PAK7) is an actin‐ and microtubule‐associated, p21cdc42/rac1 ‐activated kinase family member, which has been shown to promote proliferation, invasion, and migration of various cancer cell models." (PMID 35225431, 2022). "Previous studies confirmed that PAK5 was a key signaling molecule in cancer cells and involved in modulating tumorigenesis, anti-apoptosis and anti-cancer drugs resistance." (PMID 34340705, 2021). "In view of the fact that morphological change of the cytoskeleton greatly impacts cancer cell motility, penetration, and angiogenesis and thus results in the occurrence of nearby invasion and distant metastasis, the effects of PAK5 on cell migration and invasion were then examined." (PMID 30245957, 2018). "All these pioneering studies imply that PAK5 has a great potential to mediate cancer progression." (PMID 30245957, 2018). "These genetic data are consistent with PAK4 being more functionally relevant than PAK5 and PAK6 for these cancers, even though the three enzymes have similar domain architectures and intrinsic substrate specificities." (PMID 35969127, 2022). "In contrast, PAK3, PAK5, and PAK6 showed fewer alterations and did not exhibit strong associations with clinical outcomes in most cancer types, suggesting that their roles may be more tissue‐specific or context‐dependent." (PMID 39756822, 2025).